FAP (fibroblast activation protein alpha)
Diseases named in the same sentence as FAP in open-access papers (continued):
Sharing a sentence is not in itself a finding about the gene and the disease.
cancer (continued). "However, none of these markers are specific for myofibroblasts: FSP1 is also expressed in macrophages and cancer cells, FAP is expressed in some immune cells, and desmin and PDGFRβ are in perivascular cells." (PMID 36542704, 2022). "A wide range of cancer types has been imaged successfully with FAP-radioligands based on small molecules, particularly in those clinical conditions where imaging with [18F]FDG, the most extensively used PET radiopharmaceutical in oncology, has encountered limitations." (PMID 36015106, 2022). "FAP expression in CAFs has been described in some types of cancers." (PMID 35818720, 2022). "The majority of clinical FAP inhibitor PET scans have thus far been performed in cancer patients, but anecdotal observations of increased tracer uptake in patients with concomitant coronary artery disease attest to the potential for this technique in detecting cardiac dysfunction." (PMID 35028820, 2022). "Specifically, according to canonical markers, the three quantity-predominant major components (i.e., c1, c2, and c4) were defined as cancer-associated myofibroblasts (CAFmyo), inflammatory CAFs (CAFinfla), and adipogenic CAFs (CAFadi) by over-presenting ACTA2, FAP/TGFB1, and CFD, respectively." (PMID 36333338, 2022). "Consequently, given the overexpression of FAP in a wide variety of stromal cells during tumorigenesis, this would tend to identify the stroma as a target for anti-cancer drugs." (PMID 36263225, 2022). "Fibroblast activation protein (FAP) is overexpressed in the CAFs of numerous epithelial carcinomas and weakly expressed in healthy tissues, therefore representing an attractive target for cancer research." (PMID 34556528, 2022). "We observed that FAP was highly upregulated in most of cancers, including STAD." (PMID 35359436, 2022). "FSP1 and FAP have little expression in both normal and cancer stroma in all GS cancers." (PMID 35530322, 2022). "Studies on FAP have drawn attention to increased expression in various cancers." (PMID 35202189, 2022). "FAP inhibitors (FAPIs) have already been developed as targeted cancer drugs." (PMID 36051919, 2022). "By specifically inducing CD40 stimulation in the presence of FAP, this novel bispecific antibody was demonstrated to overcome the systemic toxicity associated with the CD40 agonist, thereby providing a promising approach for cancer immunotherapy." (PMID 36263225, 2022). "Hence, this study aimed to investigate CXCL12, CXCR4, and FAPα and their value as cancer survival factors in LARC after nCRT." (PMID 34976180, 2022). "However, combined treatment with trastuzumab and FAP-IL2v induced a pronounced anti-cancer response compared to control regimens, thus suggesting a prominent role of NK cells in driving trastuzumab/FAP-IL2v treatment efficiency." (PMID 36085201, 2022). "Besides its high expression in epithelial carcinoma, FAP also plays a key role in normal development during embryo-genesis and tissue modeling." (PMID 36531015, 2022). "Summary of studies evaluating FAP-targeted imaging of various cancer types." (PMID 34858834, 2021). "We observed that the expression of FAP in stromal cells, but not in cancer cells, was associated with GBM progression at six months after surgery." (PMID 34282761, 2021). "Increased expression of FAP was also found in pathological fibrotic diseases like idiopathic pulmonary fibrosis, liver cirrhosis and keloids as well as in stromal soft tissue of several kinds of cancer." (PMID 33667270, 2021). "However, as studies on FAP tracers in cancer began to grow in number and size, the amount of incidental findings of non-malignant diseases began to increase." (PMID 33606104, 2021). "The results from this study with respect to the selectivity of [68Ga]Ga-DOTA.SA.FAPi in various cancers may also contribute to the improvement of the already existing data on FAP molecular imaging." (PMID 34681246, 2021).
cancer (continued). "CAFs feature high expression of FAP that is not detectable in adult normal tissue but is associated with a poor prognosis in cancer patients." (PMID 33806468, 2021). "The fibroblasts encompassed 4 major populations defined by key cancer-associated fibroblast (CAF) markers, including fibroblast activation protein (FAP), alpha smooth muscle actin (αSMA, ACTA2), podoplanin (PDPN), and platelet-derived growth factor receptor beta (PDGFRβ)." (PMID 34385456, 2021). "Moreover, FAP also highly expressed in cancer cells and play an important role in regulating cancer cell biology." (PMID 34035230, 2021). "It is well established now that these FAP inhibitors show expression in various cancers." (PMID 34959613, 2021). "Fibroblast activation protein (FAP) is overexpressed in the stroma of many types of cancer." (PMID 34420105, 2021). "The expression of FAP is usually related to poor prognosis and outcomes of cancers." (PMID 35071007, 2021). "Interestingly, most of the previous studies investigating FAP’s function in cancer are relying on FAP mRNA and/or protein expression rather than on the investigation of FAP’s enzymatic activity." (PMID 33996747, 2021). "Our increasing knowledge of CAF biology has led to more pre-clinical studies developing novel FAP-targeting anti-cancer strategies that could potentially show great promise in the clinic." (PMID 33806468, 2021). "Averaging these scores across cancer types/subtypes identified many ESGs that are strongly and consistently associated with the CAF signatures, including classical CAF markers such as FAP, SPARC, THY1 (CD90) and various collagens." (PMID 33972543, 2021). "Similarly, the recent emergence of radiolabeled fibroblast activation protein (FAP) inhibitors (FAPI) with pan-cancer targeting features hints at relatively rapid adoption." (PMID 34858834, 2021). "FAP was highly expressed in cancer cells compared to normal tissues." (PMID 34035230, 2021). "Recently, 68Ga-DOTA-labelled-FAP inhibitors (FAPI) PET/CT have been used in several cancers." (PMID 34887714, 2021). "Therefore, we compared gene expression for cancer-associated fibroblast (CAF) markers including MMP2, MMP9, MMP21, TGFA, CXCL12, ITGA3, FAPα, and IL32 in fibroblasts derived from normal skin and MF tumors." (PMID 33941102, 2021). "Cancer-associated fibroblasts (CAFs) exert various immunosuppressive and pro-tumorigenic functions, including secretion of transforming growth factor beta (TGF-β), and can be targeted via FAP." (PMID 33863363, 2021). "FAP expression in HG T1 ROIs was significantly higher in progressors vs. non-progressors and was prognostic for recurrence-free survival, progression-free survival, cancer-specific survival, and overall survival." (PMID 34525114, 2021). "Haberkorn’s group reported a series of piperazine-based FAP-inhibitors labelled with the positron emitter gallium-68, which were successfully used for imaging various cancers, particularly when utilizing the most prominent molecules among their structures such as FAPI-04, FAPI-21, and FAPI-46." (PMID 34959613, 2021). "FAP’s endopeptidase activity (gelatinase activity) plays a major role in remodeling of the extracellular matrix, which is an important mechanism in the invasion and metastasis of the cancer cells." (PMID 33996747, 2021). "Importantly, this group of fibroblast cells expressed the markers for cancer‐associated fibroblasts (CAFs) including ACTA2 (encoding α‐SMA), PDGFRA, PDGFRB, DDR2, FAP, and CAV1." (PMID 34459128, 2021). "Moreover, the deletion of FAP+ CAF using a FAP-targeted immune-based therapeutic approach or a genetic ablation approach inhibited cancer growth in murine PDAC models." (PMID 34094963, 2021). "Experimental work in animal models of breast and colon cancers further suggests that in both malignant and stromal cells, FAP may be directly involved in cancer angiogenesis." (PMID 34282761, 2021).
cancer (continued). "This might be a non-specific reaction, e.g. to keratinization products; however, epithelial cancer cell expression of FAP has been reported for a variety of cancer entities including oral squamous cell cancer." (PMID 34050405, 2021). "Molecular imaging probes targeting FAP are becoming a promising broad cancer spectrum PET tracer." (PMID 33816303, 2021). "FAP is an important CAF protein associated with the outcome of several immunotherapies, and its presence in histological staining correlates with poor prognosis for most cancer patients." (PMID 34572771, 2021). "FAP is overexpressed on the cancer-related fibroblast cell membrane and TME stromal cells." (PMID 34858834, 2021). "Therefore, high levels of FAP are present in pathological conditions including fibrosis, scaring/granulation tissue, cancer, and arthritis." (PMID 33669804, 2021). "FAP-specific inhibitors (FAPIs) have already been developed as anti-cancer drugs." (PMID 33483880, 2021). "Thus, it is hardly surprising that FAP is increasingly explored as pan-cancer imaging and therapeutic target." (PMID 34226953, 2021). "Ultimately, this could provide a new convenient avenue for the development of FAP-based radiopharmaceuticals for the diagnosis and treatment of cancers predominantly." (PMID 34681246, 2021). "Moreover FAP-specific PET represents a promising imaging modality for radiotherapy planning, and various approaches to clinically target FAP are currently being studied in other cancers." (PMID 34525114, 2021). "However, despite growing research on the basic biology and functional roles of FAP in various cancers, comprehensive summaries of FAP in GBM are limited." (PMID 34068501, 2021). "Finally, we showed the applicability of both the Cy3-labeled 6 and Cy5-labeled 7 for in situ FAP labeling in cells and cancer cryosections." (PMID 33996747, 2021). "Indeed, dipeptidyl peptidase 4 (DPP4), fibroblast activated protein (FAP), and collagen type XI (COL11A1), markers of activated/cancer-associated fibroblasts, are expressed at very low levels." (PMID 33413690, 2021). "Another cancer group of interest for FAP-targeted imaging is the gastrointestinal malignancies." (PMID 34858834, 2021). "FAP was found to be highly expressed in cancer cells compared to normal epithelial cells." (PMID 34035230, 2021). "FAP molecule itself and FAP-positive cells in TME could contribute to cancer cell proliferation, invasion, angiogenesis and extracellular matrix (ECM) remodeling." (PMID 34790207, 2021). "FAP is highly expressed in many solid epithelial tumors and is correlated with worse prognosis, so it has become a novel target of interest in developing cancer therapies." (PMID 33499238, 2021). "Previous cancer studies have always confirmed fibroblasts based on the recognition of FAP and αSMA." (PMID 33634098, 2020). "Thus, careful optimisation of the binding affinity of FAP‐targeting moieties is likely to allow for the development of new cancer immunotherapies with an excellent safety profile." (PMID 33082953, 2020). "In addition, performance of therapeutic targeting at FAP also suggests its effectiveness for cancers." (PMID 33109151, 2020). "Thus, different approaches need to be implemented in targeting FAP to deplete the stromal fibroblasts in cancer." (PMID 32316521, 2020). "There is also evidence that FAP supports cancer angiogenesis." (PMID 32899119, 2020). "It follows that higher levels of soluble FAP would be expected in the plasma from cancer patients." (PMID 33207686, 2020). "Thus, CAFs, particularly those marked by FAP, are considered a promising therapeutic target for cancer therapy." (PMID 33308315, 2020). "FAP and concomitant nuclear BCAT expression in cancer cells at the infiltrating front of primary tumors and in lymph node metastases was independently associated with 5- and 10-year cancer specific and disease-free survival." (PMID 32428869, 2020).
cancer (continued). "Thus, FAP is highly expressed in fibroblasts found in chronic inflammation and fibrotic lesions, as well as in cancer tissues." (PMID 33207686, 2020). "We identified an increasing trend of FAP expression with respect to severity of cancer stages." (PMID 33109151, 2020). "Interestingly, the Bi-FAP/HER2-IL released their cargo more rapidly than the FAP-IL in FAP-expressing cancer cells, where they are taken-up based on the FAP expression levels." (PMID 33076292, 2020). "However, CAFs frequently express fibroblast activation protein alpha (FAPα), making them distinguishable from healthy cells and a potential target for cancer treatment." (PMID 33287413, 2020). "Thus, it is believed that anti-cancer (αSMA+/FAPα−) fibroblasts have higher Hedgehog signaling with lower negative regulators, Ptch 1/2, and higher positive regulators, Smo." (PMID 32485981, 2020). "In addition, FAP had a consistent expression profile between carcinoma-paracarcinoma and early-advanced stages of HGSOC." (PMID 33109151, 2020). "Combination of viral oncolysis of cancer cells and FBiTE-mediated cytotoxicity of FAP-expressing CAFs might be an effective strategy to overcome a key limitation of oncolytic virotherapy, encouraging its further clinical development." (PMID 30683154, 2019). "Previous research showed that FAP+ CAFs contribute to the invasive behavior of cancer cells." (PMID 30922247, 2019). "Future functional experiments should investigate the contribution of FAP to cancer cell invasion." (PMID 30922247, 2019). "The increased expression of FAP at the invasive part and in stroma-high tumors might contribute to the invasive behavior of cancer cells." (PMID 30922247, 2019). "The ability of FAP to affect cancer cell behavior might explain why the present study found an increased expression of FAP at the invasive part and in stroma-high tumors, known to be more aggressive than stroma-low tumors." (PMID 30922247, 2019). "Thus, caution should be taken when designing FAP-targeting approaches for clinical testing in cancer patients." (PMID 31428105, 2019). "Furthermore, the anti-FAP antibody sibrotuzumab labeled with 131I was applied for the treatment of patients with metastasized FAP-positive carcinomas." (PMID 31659499, 2019). "Stromal FAP could be a potential prognostic biomarker in GC by promoting cancer progression via EMT through Wnt/ β-catenin signal pathway." (PMID 30419872, 2018). "However, the full diversity of cancers and other diseases in which FAP+ HO-1+ macrophages can play a role has yet to be established." (PMID 30054470, 2018). "Cancer-associated fibroblasts feature high expression of fibroblast activation protein (FAP), which is not detectable in adult normal tissue but is associated with a poor prognosis in cancer patients." (PMID 29626120, 2018). "Moreover, we showed, in TCGA network of variant cancers and the ovarian microdissected profile, that SNAI2 was positively related with classical CAF activation markers, such as ACTA2, FAP, and PDGFRB." (PMID 29041931, 2017). "Circulating FAPα levels were demonstrated significantly lower in cancer patients compared with healthy subjects and correlated inversely with survival in most types of cancer." (PMID 28415791, 2017). "Staining for FAP in epithelial cancer cells was mostly negligible." (PMID 28531107, 2017). "Importantly, a large body of research in cancer and inflammation concur that FAP expression defines reactive stromal fibroblasts at sites of inflammation and remodelling." (PMID 28158223, 2017). "Although the exact function of FAP α in the development of the different diseases remains unclear, it is believed to participate in the progression and metastasis of cancer, angiogenesis, and the suppression of the antitumor response of the immune system." (PMID 26985769, 2016).
cancer (continued). "Eliminating FAP α+ stromal fibroblasts activating cancer-specific T cells should inhibit growth of small spontaneous tumors and thus may help eliminate clinically undetectable cancer cells that have already metastasized before excision of the primary tumor." (PMID 26985769, 2016). "Combined immunotherapy treatment with T cells that target cancer cells and an additional agent that targets FAP α-expressing cells for destruction could increase the success of solid tumor elimination." (PMID 26985769, 2016). "Furthermore, because of the multiple roles played by FAP α in neoangiogenesis, invasion and metastasis, it is being explored as a target for cancer therapy." (PMID 26985769, 2016). "In this section, we will examine the role of FAP α in different carcinomas." (PMID 26985769, 2016). "A phase I open-label study demonstrated that a humanized antibody (sibrotuzumab), directed against human FAPα expressed by advanced or metastatic FAPα-positive cancer, may be administered safely." (PMID 25593080, 2015). "Fibroblast activation protein α (FAPα) is a potential target for cancer therapy." (PMID 26305550, 2015). "It has been reported that FAP is expressed exclusively in stromal fibroblasts of epithelial cancers, though some reports have suggested that FAP is expressed in both the stromal and epithelial compartments of cancers." (PMID 26330349, 2015). "FAP is best known for its presence in stromal CAFs, found in over 90 % of epithelial tumors, even though it is also expressed in reactive fibroblasts during embryonic development, wound healing, chronic inflammation and in cancer cells." (PMID 26330349, 2015). "In the context of immunotherapy involving T cells targeting cancer cells, an agent targeting FAPα-expressing cells might increase therapeutic efficacy against both solid tumors and metastatic cells." (PMID 26305550, 2015). "Furthermore, because of the multiple roles played by FAPα in neoangiogenesis, invasion and metastasis, it is frequently explored as a target for cancer therapy." (PMID 26305550, 2015). "For comparison, there was little FAP protein in 293T cells, an epithelial type of cancer cell." (PMID 24551161, 2014). "FAP has been intensively investigated as a potential diagnostic or therapeutic target since it is overexpressed by activated stromal fibroblasts in malignant tumors and is absent in normal adult tissues and benign tumors." (PMID 24520291, 2014). "The cancer-specific distribution of FAP makes it a novel therapeutic target in cancer treatment." (PMID 24520291, 2014). "We tentatively suggest that the negative result in the earlier studies might be due to the comparative difference in staining intensity between the high expressions in stromal cells compared to the weaker expression of FAP-α in cancer cells." (PMID 24885257, 2014). "In those studies, both wild-type and proteolytically inactive mutants of FAP could promote cancer cell growth." (PMID 24551161, 2014). "Apparently, the FAP-transfected cancer cells continuously provided the source that allowed aggregate formation of the fusion protein such that strong cytotoxicity against the Fas+ cancer cells could be induced." (PMID 23497165, 2013). "We generated a tetracycline-inducible FAP overexpressing fibroblastic cell line to synthesize an in vivo-like 3-dimensional (3D) matrix system which was utilized as a stromal landscape for studying matrix-induced cancer cell behaviors." (PMID 21668992, 2011). "Also, FAP+ matrix-induced regulatory molecules in cancer cells were determined by Western blot analyses." (PMID 21668992, 2011). "Thus FAP+ matrices were utilized as a stromal landscape to study matrix-induced pancreatic (and in some instances breast) cancer cell behaviors." (PMID 21668992, 2011). "However, some studies have reported contradictory results regarding FAP's role in other cancers." (PMID 41410015, 2026).